VEGFC (vascular endothelial growth factor C)
Diseases named in the same sentence as VEGFC in open-access papers (continued):
Sharing a sentence is not in itself a finding about the gene and the disease.
Alzheimer disease (9 papers, 2021 to 2025). A progressive, neurodegenerative disease characterized by loss of function and death of nerve cells in several areas of the brain leading to loss of cognitive function such as memory and language. "Discovery of meningeal lymphatic vessels (LVs) in the dura mater, also known as dural LVs (dLVs) that depend on vascular endothelial growth factor C expression, has raised interest in their possible involvement in Alzheimer’s disease (AD)." (PMID 39087029, 2024). "ACSL3 mitigates Alzheimer’ s disease pathology by activating the brain-derived neurotrophic factor (BDNF) and vascular endothelial growth factor C (VEGF-C) signaling pathways, with its underlying mechanism potentially linked to the synthesis of ω−3 and ω−6 FAs." (PMID 41288931, 2025). "It was further shown that vascular endothelial growth factor C (VEGF-C) treatment potentiated immunotherapies against amyloid beta, leading to better outcomes in mouse models of Alzheimer’s disease, elucidating the important roles that the meningeal lymphatic system may play in neurological disease." (PMID 35327593, 2022). "Ten DEGs, including IGF1, VEGFC, RAPGEF3, PIK3CA, Akt3, ITGB3, ITGA11, SPP1, NOS1, and ATP6V0B, were selected from Rap1, oxidative phosphorylation, and Alzheimer’s disease signaling pathways." (PMID 34359260, 2021).
gastric tumor (9 papers, 2003 to 2025). "The surface of calcium carbonate nanoparticles coated with siRNA was shown effective in the suppression of vascular endothelial growth factor C (VEGF-C) in gastric tumors." (PMID 33920840, 2021).
head and neck squamous cell carcinoma (9 papers, 2010 to 2025). A squamous cell carcinoma that arises from any of the following anatomic sites: lip and oral cavity, nasal cavity, paranasal sinuses, pharynx, larynx, and salivary glands. "It has also been reported that VEGFC expression is related to tumor progression in head and neck squamous cell carcinomas." (PMID 38203550, 2023). "TIMER2.0 was used to analyze whether YAP1/VEGFC signaling pathway is involved in lymphangiogenesis in head and neck squamous cell carcinoma (HNSCC)." (PMID 37974224, 2023). "Moreover, VEGFA, VEGFB, VEGFC, and PGF expression was significantly increased in CHOL, head and neck squamous cell carcinoma (HNSC), KIRC, and LIHC tumor tissues." (PMID 37852616, 2023).
metastatic tumors (9 papers, 2009 to 2026). "Our statistical analysis revealed that the expression level of SOAT1 was higher in LN-metastatic tumors and was positively correlated with the expression level of VEGFC, VEGFR3 and LYVE-1, which are lymphangiogenic growth factors." (PMID 34790132, 2021). "Vascular endothelial growth factor-C (VEGF-C) was by far the angiogenesis-related gene that showed the largest difference in expression level between high IFP/highly metastatic tumors and low IFP/poorly metastatic tumors in the BxPC-3 model." (PMID 28624797, 2017). "Since LAM muscle cells express two lymphangiogenic growth factors—vascular endothelial growth factor C (VEGF-C) and vascular endothelial growth factor D (VEGF-D)—and disseminate through the lymphatic system, LAM is considered a low-grade metastatic neoplasm." (PMID 39858105, 2025).
primary lymphedema (9 papers, 2017 to 2026). A congenital condition that results in swelling in the arms or legs, and can occur during adolescence or adulthood. "One possible explanation of a mild etiology of congenital primary lymphedema of Gordon is the possible compensation for the loss of VEGFC by other factors such as VEGFD since the mature form of human VEGFD binds both VEGFR2 and VEGFR3." (PMID 30071673, 2018). "Mutations in the transcription factor-coding gene SOX18, the growth factor-coding gene VEGFC and its receptor-coding gene VEGFR3/FLT4 cause primary lymphedema in humans." (PMID 37759531, 2023). "Vascular endothelial growth factor C (VEGF-C) induces lymphangiogenesis via VEGF receptor 3 (VEGFR3), which is encoded by the most frequently mutated gene in human primary lymphedema." (PMID 35763346, 2022). "VEGFC-dependent VEGFR3 phosphorylation and FLT4 expression were reduced in cells with c.3175G>C FLT4 variant compared to wild-type, confirming the pathogenic role of c.3175G>C in primary lymphedema." (PMID 41614898, 2026).
cholangiocarcinoma (8 papers, 2013 to 2023). A carcinoma that arises from the intrahepatic biliary tree (intrahepatic cholangiocarcinoma) or from the junction, or adjacent to the junction, of the right and left hepatic ducts (hilar cholangiocarcinoma). "Among all 10 prognostic specific immune-related genes, 4 genes (AKT1, EPO, MUC4, VEGFC) were considered as important predictors of relapse-free or overall survival and were implicated in immune microenvironment-related pathogenesis of cholangiocarcinoma." (PMID 36817485, 2023). "RiskScore of cholangiocarcinoma patients with 10 genes calculated followed the formula: The RiskScore=0.429*VEGFC -0.434*NFKBIA-0.884*NLRX1+0.54*AKT1+0.629*CSRP1+0.406*EPO+0.833*IL31RA+1.023*LEP+0.341*MUC4+0.363*SEMA4B." (PMID 36817485, 2023). "Researches have shown that TWIST1 dependent VEGFC expression promoted the progression of cholangiocarcinoma." (PMID 35152264, 2022).
Lipedema (8 papers, 2020 to 2025). Disorder of adipose tissue characterized by symmetric and bilateral enlargement of the lower extremities due to abnormal deposition of subcutaneous fat often in obese women. "For example, blood serum from human lipedema patients had increased systemic VEGFC, which may have contributed to an increase in macrophage infiltration, yet there was no discernable change in LVD found in corresponding patient lipedema tissues." (PMID 38218743, 2024).
Peritoneal Fibrosis (8 papers, 2015 to 2023). Disorder characterized by a wide range of structural changes in PERITONEUM, resulting from fibrogenic or inflammatory processes. "The TGFβ‐VEGFC pathway stimulates the production of VEGFC in tubular epithelial cells, macrophages and mesothelial cells, resulting in lymphangiogenesis in renal and peritoneal fibrosis." (PMID 37026377, 2023).
rheumatoid arthritis (8 papers, 2019 to 2024). A chronic, systemic autoimmune disorder characterized by inflammation in the synovial membranes and articular surfaces. "VEGFC gene also plays an important role in the development of various autoimmune diseases such as rheumatoid arthritis." (PMID 35865663, 2022). "CCBE1 ADAMTS3, VEGFC, FLTR4, and GJC2 are thought to be related with either Hennekam disorder or its related symptoms in many diseases, including rheumatoid arthritis." (PMID 34234628, 2021). "Vascular endothelial growth factor C (VEGF-C) promotes angiogenesis, a prominent feature in rheumatoid synovitis, contributing to the perpetuation of the global burden of rheumatoid arthritis (RA)." (PMID 31692815, 2019).
lymphatic malformation (7 papers, 2021 to 2025). Primary lymphedema is caused by anatomic or functional defects in the lymphatic system, resulting in chronic swelling of body parts and lymphatic-system malformation. "This is in contrast to cutaneous lymphatic malformations, where the related lymphangiogenic growth factor VEGFC is essential for Pik3ca-driven vessel overgrowth." (PMID 40410415, 2025).
nasopharyngeal carcinoma (7 papers, 2013 to 2025). A carcinoma arising from the nasopharyngeal epithelium. "In conclusion, this study demonstrates that elevated serum levels of VEGFC, VEGFR-3, and IGF1 are significantly associated with metastasis and poor prognosis in patients with nasopharyngeal carcinoma." (PMID 41333209, 2025). "Furthermore, a study showed that silencing VEGFC can increase the radiosensitivity of nasopharyngeal carcinoma CNE-2 cells." (PMID 36203528, 2022).
osteosarcoma (7 papers, 2012 to 2024). A usually aggressive malignant bone-forming mesenchymal neoplasm, predominantly affecting adolescents and young adults. "Genes involved in epithelial cell proliferation, such as BCL11B, NRAS, THBS1, and VEGFC, promote angiogenesis and tumorigenesis, reflecting the heterogeneity of osteosarcoma-related genes." (PMID 35610231, 2022). "The MIAT/miR-128-3p/VEGFC pathway contributed to the development of osteosarcoma and may even be used as a potential therapeutic target for OS." (PMID 36793341, 2022).
renal fibrosis (7 papers, 2021 to 2025). A final common manifestation of a wide variety of chronic kidney diseases characterized by glomerulosclerosis and tubulointerstitial fibrosis. "This question is a critical aspect of our ongoing study, since understanding the role of MR activation in modulating VEGFC production by macrophages could shed light on the complex mechanisms driving lymphangiogenesis in the context of renal fibrosis." (PMID 38693148, 2024). "In a mouse model of renal fibrosis and ischemia reperfusion, CTGF knockdown resulted in a significant reduction in VEGFC and lymphatics, suggesting that CTGF contributes to VEGFC secretion and lymphangiogenesis." (PMID 37762426, 2023).
Sepsis (7 papers, 2015 to 2026). Sepsis is defined as life-threatening organ dysfunction caused by a dysregulated host response to infection. "However, miR-15a can potentially promote NF-ΚB signaling by negatively regulating IKK-α and inhibit genes encoding vascular endothelial growth factor (VEGF)A, VEGFC, and myosin light chain kinase, increasing vascular permeability in sepsis." (PMID 35305556, 2022). "In the present study, we investigated the effects of sepsis on the meningeal lymphatic system and examined whether overexpression of lymphangiogenic vascular endothelial growth factor c (VEGF-C) improves sepsis-induced neuroinflammation and cognitive impairment." (PMID 38287311, 2024). "First, both miR-15a and miR-27a are known to or are predicted to target and inhibit genes that increase vascular permeability in the setting of sepsis including VEGFA, VEGFC and MYLK." (PMID 26683209, 2015).
skin cancer (7 papers, 2010 to 2023). "In another skin cancer, MM, the expression of VEGFC, VEGFR2, and VEGFR3 was reported to be significantly higher in the metastatic tissues." (PMID 38203550, 2023). "Vascular endothelial growth factor-C (VEGF-C) has been implicated in epithelial-mesenchymal transition (EMT) processes and various human cancers, including skin cancer." (PMID 27901498, 2017).
Ureteral obstruction (7 papers, 2012 to 2025). Obstruction of the flow of urine through the ureter. "We found that the activation of mineralocorticoid receptors and the increase in vascular endothelial growth factor C in the contralateral kidney after unilateral ureteral obstruction could promote lymphangiogenesis." (PMID 38693148, 2024).
Arthritis (6 papers, 2007 to 2025). Inflammation of a joint. "It is evident that excess salt intake alters the endothelial function increasing production of TGF‐β and modulating vascular endothelial growth factor C (VEGF‐C) and increasing risk of arthritis." (PMID 35959275, 2022).
cardiac hypertrophy (6 papers, 2020 to 2026). "Similarly, the absence of VEGFC/VEGFR3 signaling in mouse models of cardiac hypertrophy increases cardiac hypertrophy and dysfunction, while VEGFC transmission improves hypertrophy and delays the development of centripetal heart failure." (PMID 36831512, 2023).
coronary artery disease (6 papers, 2014 to 2025). "In patients with coronary artery disease, vascular endothelial growth factor C/D (VEGFC/D) was verified to be predictors of mortality." (PMID 34180125, 2021).
Hypercholesterolemia (6 papers, 2011 to 2021). An increased concentration of cholesterol in the blood. "Indeed, ablation of lymphatic systems by Chy-mutation as well as depletion of lymphangiogenic factors, including vascular endothelial growth factor-C and -D, in mice perturbs lipoprotein composition to augment hypercholesterolemia." (PMID 34250049, 2021).
Papillary Thyroid Carcinoma (6 papers, 2010 to 2022). "Papillary thyroid carcinoma cell line TPC-1 displayed high levels of SRC-1 and VEGFC expression and was selected for stable knockdown of SRC-1 in vitro." (PMID 29717026, 2018).
diabetic kidney disease (5 papers, 2018 to 2025). Progressive kidney disorder caused by vascular damage to the glomerular capillaries, in patients with diabetes mellitus. "In diabetic nephropathy, pro-inflammatory M1 macrophages participate in the development of lymphangiogenesis by stimulating vascular endothelial growth factor-C (VEGF-C) and transdifferentiate into lymphatic endothelial cells." (PMID 36405700, 2022). "In diabetic kidney disease, VEGFC induced lymphangiogenesis in association with fibrosis through transforming growth factor-β (TGFβ) and connective tissue growth factor (CTGF) mediated upregulation of VEGFC expression." (PMID 30551619, 2018). "VEGFC highly expressed in macrophages in rat residual kidney tissue, mice with UUO, human IgA nephropathy biopsy samples, diabetic kidney disease (DKD), and chronic allograft rejection." (PMID 38693148, 2024).
gallbladder cancer (5 papers, 2014 to 2025). "Besides, researchers have found that TNF-α could upregulate VEGFC expression, promoting lymphangiogenesis and lymphatic metastasis in gallbladder cancer." (PMID 37124061, 2023).
hemangioma (5 papers, 2016 to 2022). A benign vascular lesion characterized by the formation of capillary-sized or cavernous vascular channels. "In contrast, the expression of VEGFC has been found limited to neoplastic endothelial cells in hemangiomas with capillary differentiation." (PMID 32756451, 2020).
ischemia (5 papers, 2019 to 2025). A hypoperfusion of the BLOOD through an organ or tissue caused by a PATHOLOGIC CONSTRICTION or obstruction of its BLOOD VESSELS, or an absence of BLOOD CIRCULATION. "In contrast, microglia cells produce vascular endothelial growth factor C (VEGF‐C) following ischemia, which stimulates the proliferation of OPCs via the VEGFR‐3 receptor." (PMID 37905592, 2023). "Glinton and colleagues considered the complexity of the immune, fibrotic, and angiogenic responses in the heart following ischemia and investigated the role of myeloid VEGFC in the immune response during cardiac repair." (PMID 35499075, 2022). "In summary, by using the model of lung injury with cerebral ischemia, we found that VEGFC is useful for neurons in the brain to protect itself during the ischemia, but that it is harmful in lung tissue." (PMID 31191213, 2019). "It appears that the cerebral tissue may express more VEGFC to protect itself during the ischemia, but it is harmful in lung tissue." (PMID 31191213, 2019). "It remains to be determined whether other efferocytosis-triggered angiogenic factors besides VEGFC, such as VEGFA, promote lymphangiogenesis and vascular angiogenesis after ischemia." (PMID 35499075, 2022).
Lymphatic Metastasis (5 papers, 2013 to 2023). Transfer of a neoplasm from its primary site to lymph nodes or to distant parts of the body by way of the lymphatic system. "According to all above, we came to a conclusion that NOTCH1 was indispensable for MIR503HG-mediated VEGFC secretion in pRCC-associated lymphatic metastasis." (PMID 37416763, 2023).
pancreatic neuroendocrine tumor (5 papers, 2010 to 2022). Pancreatic endocrine tumor, also known as pancreatic neuroendocrine tumor (PNET), describes a group of endocrine tumors originating in the pancreas that are usually indolent and benign, but may have the potential to be malignant. "Pancreatic neuroendocrine tumors are also associated with C-MYC overexpression which also promotes vascular endothelial growth factor C (VEGFC) expression the development of lymphatic endothelial cells." (PMID 36090051, 2022). "The authors suggested that c-Myc is overexpressed in the case of pancreatic NETs, which is also associated with the VEGF pathway and increased expression and secretion of vascular endothelial growth factor C (VEGF-C)." (PMID 35372578, 2022). "c‐Myc promotes lymph node metastases of pancreatic neuroendocrine tumors via upregulation of vascular endothelial growth factor C (VEGFC)." (PMID 33128283, 2021).
Pulmonary lymphangiectasia (5 papers, 2016 to 2021). Abnormal dilatation of the pulmonary lymphatic vessels. "The activation of human lung mast cells may induce the release of lymphangiogenic factors including vascular endothelial growth factor C which can result in pulmonary lymphangiectasia and pleural effusions." (PMID 35011785, 2021).
tongue squamous cell carcinoma (5 papers, 2018 to 2024). A squamous cell carcinoma that arises from the tongue. "It was reported in tongue SCC that the high immunohistochemical expression of vascular endothelial growth factor C (VEGF-C), vascular endothelial growth factor receptor 3 (VEGFR-3), CCR7 and semaphorin 3E (SEMA3E) are predictors of metastasis." (PMID 31011147, 2019). "It has been found to be extensively involved in tumor progression in tongue squamous cell carcinoma (SCC), as its expression together with that of vascular endothelial growth factor C (VEGF-C) were considerably higher in pre-invasive lesions and invasive neoplasia." (PMID 38489333, 2024).
viral infection (5 papers, 2020 to 2025). "Conversely, prophylactic administration of vascular endothelial growth factor C (VEGF-C) attenuated viral infection-induced pathology." (PMID 40144621, 2025). "However, vascular endothelial growth factor C (VEGF-C) pretreatment promotes recovery of MLV functions against viral infection." (PMID 38931455, 2024).
Cerebral ischemia (4 papers, 2019 to 2025). Restriction of arterial blood supply to the brain associated with insufficient oxygenation to support the metabolic requirements of the tissue. "We found that the VEGFC increased in lung injury caused by cerebral ischemia, and siVEGFC in vitro, confirmed VEGFC is a key protein in lung injury with cerebral ischemia." (PMID 31191213, 2019). "The up-regulation of VEGFC in neurons and lung cells suggested that VEGFC has been involved in the process of brain ischemia with lung injury." (PMID 31191213, 2019). "Therefore, we confirmed the different role of VEGFC played in neurons and lung cells in cerebral ischemia-reperfusion injury." (PMID 31191213, 2019). "Therefore, we explored the connection of VEGFC and lung injury induced by cerebral ischemia to provide primary evidence in understanding the role of VEGFC for further preclinical application." (PMID 31191213, 2019). "In this study, VEGFC was found as an over-expression protein in the model of lung injury induced by cerebral ischemia, which has not been reported in recent literature." (PMID 31191213, 2019).
Chylothorax (4 papers, 2017 to 2021). The presence of chyle in the thoracic cavity. "Additionally, overexpression of vascular endothelial growth factor C (VEGFC) in adipocytes resulted in the incompetence of LVs (likely due to the dilation of lymphatic vessels) and in chylothorax." (PMID 29125824, 2017).
congenital primary lymphedema (4 papers, 2016 to 2023). "Therefore, the three mouse models are very similar to the human phenotypes of the VEGFR3-associated Milroy disease and the VEGFC-associated congenital primary lymphedema of Gordon." (PMID 30071673, 2018). "Sanger sequencing identified no pathogenic variants in the genes known to be associated with congenital primary lymphedema (i.e., CCBE1, VEGFR3, and VEGFC) in the UK proband (GLDUK:I.2)." (PMID 27400125, 2016). "Future work should be conducted to further elucidate the interaction of VEGFC and VEGFR3 as well as to try and identify the reason for inter-familial and intra-familial variation in both Milroy disease and congenital primary lymphedema of Gordon." (PMID 30071673, 2018).